TLR4 (toll like receptor 4)
Diseases named in the same sentence as TLR4 in open-access papers (continued):
Sharing a sentence is not in itself a finding about the gene and the disease.
leptospirosis (continued). "Overall, further investigation will be necessary to clarify the role of TLR4 in controlling leptospirosis." (PMID 35937697, 2022). "Our group showed in the murine model of leptospirosis that TLR4-dependent IgM produced as early as 3 days postinfection was partially protective." (PMID 35937697, 2022). "The role of TLR4 in the resistance of the mouse model has been extensively addressed: C3H/HeJ and TLR4-/- mice are sensitive to leptospirosis." (PMID 35937697, 2022). "Like humans, TLR4 knock-out mice are sensitive and can die from acute leptospirosis, and we showed that TLR4 has a crucial role in mounting the protective anti-Copenhageni IgM response." (PMID 33705392, 2021). "It has been shown that TLR4 plays a critical role in controlling bacterial load and developing severe leptospirosis in mice." (PMID 34975922, 2021). "This study is significant as it indicates that one intact TLR4 gene, be it mouse or human, is necessary to control acute leptospirosis." (PMID 33519799, 2020). "The early induction of TLR2, TLR4 and inflammatory factor is important for controlling leptospirosis." (PMID 31914888, 2020). "As a control we used a congenic mutant strain in which the tlr4 coding sequences are deleted (muTLR4Lps-del), as we expected it to develop leptospirosis as shown for other C57BL/6J TLR4KO mice." (PMID 33519799, 2020). "We previously showed that leptospiral LPS is not recognized by the human-TLR4, whereas it signals through mouse-TLR4 (mTLR4), which mediates mouse resistance to acute leptospirosis." (PMID 32790743, 2020). "Since the delay in inflammation correlates with higher pathogenicity of leptospira, we studied the effect of inducing inflammation on leptospirosis by using TLR4 activator LPS." (PMID 31914888, 2020). "The species specificity of TLR4 recognition most likely explains the differences in the severity of leptospirosis, which can be fatal in humans but asymptomatic in mice that are considered chronic carriers of Leptospira." (PMID 33123147, 2020). "Emerging evidence has proven that TLR2 and TLR4 play a crucial role in the development of leptospirosis." (PMID 31675378, 2019). "This suggests the potential of combining TLR4 blockade and antibiotics in the treatment of severe leptospirosis with manifestations of pulmonary hemorrhage." (PMID 28536433, 2017). "Considering that L06vLPS signals mainly through TLR4, we therefore infected TLR4−/− mice with strain 56606v to explore the role of L06vLPS interaction with TLR4 in the pathogenesis of acute leptospirosis." (PMID 28536433, 2017). "Of note, humans, also believed to be susceptible to leptospirosis express a TLR4 molecule that does not sense the atypical Leptospira LPS." (PMID 39975062, 2025). "Our data strongly suggests that TLR4 function is important but not sufficient to cause susceptibility to leptospirosis." (PMID 39975062, 2025). "Besides the role of TLR2 in response to leptospirosis, the involvement of TLR4 and TLR5 was identified in in-vitro and in-vivo studies." (PMID 39729468, 2024). "Our MESV against Leptospirosis demonstrated strong antigenicity, conservation, and safety, successfully eliciting robust immune responses, and showed broad population coverage with strong interactions with TLR4 and TLR2." (PMID 39936152, 2024). "Considering the crucial roles of TLR2 and TLR4 in protecting against leptospirosis and recognizing the potent adjuvant effects of MPLA, it was of interest to assess the adjuvant potential of the naturally less toxic Leptospira LPS, specifically lipid A, against leptospirosis." (PMID 38140228, 2023). "This study concludes that the presence of a functional TLR4 gene, whether murine or human, is the prerequisite for resistance to acute leptospirosis." (PMID 35937697, 2022). "It has long been known that TLR4 is important in controlling leptospirosis, as mice lacking TLR4 are susceptible to acute disease." (PMID 35923802, 2022).
leptospirosis (continued). "TLR4 therefore plays an unequivocal role in the response to leptospirosis." (PMID 35937697, 2022). "Among TLRs, TLR2 and TLR4 are the most studied in leptospirosis now." (PMID 36551258, 2022). "We therefore hypothesized that C57BL/6J mice carrying the human TLR4/MD-2 receptor and co-receptor in its immune cells (huTLR4) should be more sensitive to sublethal leptospirosis than wild-type congenic C57BL/6J (WT)." (PMID 33519799, 2020). "In view of the important role of TLR4 in controlling leptospirosis, so we hypothesized that TLR4 receptor agonist LPS could help control leptospirosis, and tested the efficacy of LPS in the resistance of leptospirosis." (PMID 33232366, 2020). "In view of the important role of TLR4 in the control of leptospirosis." (PMID 33232366, 2020). "However, we found that dissemination of Leptospira interrogans serovar Copenhageni FioCruz in blood, shedding in urine, colonization of the kidney and overall kinetics of leptospirosis progression is equivalent between mice carrying murine and human TLR4." (PMID 33519799, 2020). "In consideration of the modest efficacy of TLR2 agonist Pam3CSK4 against leptospirosis, we hypothesized that TLR4 agonist lipopolysaccharide (LPS) could provide better protection." (PMID 31914888, 2020). "If human TLR4 does not sense the atypical Leptospira LPS, huTLR4 mice should have been more permissive of Leptospira escape and more susceptible to leptospirosis than wild-type." (PMID 33519799, 2020). "BALB/c that presents TLR4+ has a greater ability to early modulation of chemokines expression, suggesting a relationship between resistance mechanisms and early modulation of chemokines in leptospirosis diseases." (PMID 30616505, 2019). "Later on, C3H/HeN mice that do not have the point mutation in TLR4 were infected in parallel with C3H/HeJ mice, and proven resistant to death, providing further evidence that TLR4 is important to control leptospirosis." (PMID 28270811, 2017). "Thus, it is possible that the increased production of inflammatory mediators in leptospirosis is related both to recognition mechanisms involving TLR4 and fatty acid receptors and to a mechanism dependent on Na/K-ATPase signaling." (PMID 23132959, 2012). "During leptospirosis, bacterial recognition by host is under disclosure, but Leptospira presence may be sensed through TLR4 and TLR2 receptors." (PMID 23132959, 2012). "Thus, competent recognition of leptospiral-LPS by murine TLR4 plays a role but it is not sufficient to determine susceptibility to leptospirosis." (PMID 39975062, 2025). "Our data suggests that TLR4 function is not sufficient to cause susceptibility to leptospirosis." (PMID 40445994, 2025). "Thus, competent recognition of L. interrogans serovar Copenhageni FioCruz factors by murine TLR4 does not determine susceptibility to leptospirosis." (PMID 40445994, 2025). "However, mouse strains that express an impaired TLR4 in their immune cells (C3H-HeJ) are susceptible to lethal and sublethal leptospirosis and those that have been engineered to not express TLR4 (C57BL/6J-TLR4ko) succumb to infection." (PMID 34249775, 2021). "Nevertheless, certain mouse strains, such as C3H/HeJ and TLR4/TLR-2 double knockout mice, have proven to be valuable experimental models for leptospirosis research." (PMID 41251377, 2025). "Nevertheless, the two mouse strains with a fully functional tlr4 gene (C3H-HeN and C57BL/6) also developed clinical and molecular signs of sublethal leptospirosis over two weeks of infection, nearly on par with C3H-HeJ." (PMID 39975062, 2025). "Our data indicates that TLR4-competent C3H/HeN and C57BL/6 are appropriate mouse models of sublethal leptospirosis." (PMID 40445994, 2025). "Even though TLR4 is the most defensive PRR in mice/hamster models against leptospirosis, TLR2 contributed to triggering the immune response." (PMID 39729468, 2024).
leptospirosis (continued). "The contribution of both TLR4 and TLR2 in leptospirosis pathogenesis was observed in DKO mice by showing dramatically low mRNA expression of IFNγ and iNOS, compared with WT mice." (PMID 39729468, 2024). "In the context of leptospirosis, considerable attention has been directed toward Toll-like receptors, particularly TLR2 and TLR4, within the TLR family." (PMID 38476949, 2024). "Recognition of leptospires by TLR4 and TLR2 was therefore shown to be essential to the resistance of the murine model to acute leptospirosis." (PMID 35899053, 2022). "It has been demonstrated that leptospiral LPS activates the plasma membrane Toll-like receptor 2 (TLR2) instead of TLR4 for signaling in humans cells, whereas in mice, which are resistant to acute leptospirosis, both TLR2 and TLR4 recognize leptospiral LPS." (PMID 32932775, 2020). "In this study, we show that treatment with LPS promoted the gene expressions of TLR2, TLR4, NLRP3 and downstream cytokines, all of which would help control leptospirosis." (PMID 31914888, 2020). "Thus, activating host TLR4 may be the key to the treatment of leptospirosis." (PMID 33232366, 2020). "Therefore, targeting TLR4 may be an effective way to against leptospirosis in the future." (PMID 33232366, 2020). "The rationale for using humanized TLR4 transgenic mice is that, if human TLR4 does not sense the atypical leptospiral-LPS, these mice should be more permissive of Leptospira escape and more susceptible to leptospirosis than wild-type mice expressing murine TLR4 that do sense leptospiral-LPS." (PMID 33519799, 2020). "Researchers working on the function of the host TLR4 in leptospirosis used immunocompetent C57BL/6J and its respective congenic TLR4 knockouts." (PMID 33519799, 2020). "Here we report milder pulmonary and subcutaneous hemorrhage in TLR4−/− mice than in WT mice, suggesting that TLR4 contributes, at least partially, to hemorrhage in leptospirosis." (PMID 28536433, 2017). "Recently, a study using mice showed that TRIF, the adaptor of TLR4 and also TLR3, the receptor of viral RNA, has a protective role during leptospirosis." (PMID 28270811, 2017). "During early stages of leptospirosis, leptospiral LPS and outer membrane lipoproteins induce inflammation primarily via Toll-like receptor 2 (TLR2) and in some experiments, via TLR4 activation." (PMID 28750011, 2017). "Other than protective responses resulting from the stimulation of both TLR4 and TLR2, it was shown that leptospirosis induced a TLR2- and TLR4-independent inflammation, also independent from other TLRs." (PMID 28270811, 2017). "We recently showed that TLR2, TLR4, and NLRP3 receptors were crucial in the defense against leptospirosis." (PMID 24498450, 2014). "Our data indicates that TLR4-competent C3H-HeN and C57BL/6 may be more appropriate mouse models of sublethal leptospirosis, whereas C3H-HeJ may be good model of lethal leptospirosis." (PMID 39975062, 2025). "Because it is not known how Leptospira activate TLRs in dogs, we investigated whether canine TLR4 and TLR2 are involved in the recognition of four inactivated Leptospira strains, present in vaccines against canine leptospirosis." (PMID 35386703, 2022). "In mice, which are resistant to leptospirosis, the LPS is recognized by both TLR2 and TLR4." (PMID 36551258, 2022). "In addition to TLR4, we also explored the involvement of canine TLR2 in the recognition of four Leptospira strains commonly used in vaccines against canine leptospirosis." (PMID 35386703, 2022). "Indeed, when studying the general course of leptospirosis, TLR2 and TLR4 play a key role in the control of L. interrogans." (PMID 35899053, 2022). "Other studies in C3H/HeJ mice naturally not expressing TLR4 have described humoral and cellular responses upon experimental leptospirosis with Copenhageni Fiocruz L1-130, but only total, not Leptospira-specific Igs have been studied." (PMID 33705392, 2021).
leptospirosis (continued). "Toll-Like Receptor (TLR) 4, the LPS receptor, plays a central role in the control of leptospirosis and absence of TLR4 results in lethal infection in mice." (PMID 33519799, 2020). "To find out if replacing the murine TLR4 with human TLR4 affects the kinetics of leptospirosis progression, we compared infection in wild-type C57BL/6J (WT) and humanized TLR4/MD2 transgenic mice (huTLR4) and added a congenic murine mutant lacking the TLR4 receptor as control (muTLR4Lps-del)." (PMID 33519799, 2020). "We previously showed that Myd88 ko mice are very sensitive to, and die from, acute leptospirosis because of a lack of TLR4 recognition." (PMID 25474719, 2014). "Thus, TLR4-competent C3H-HeN and C57BL/6 may be more appropriate mouse models of sublethal leptospirosis, whereas C3H-HeJ can be used to further establish a mouse model of lethal leptospirosis." (PMID 39975062, 2025). "Indeed, both TLR4 and TLR2 stimulation is important in controlling leptospirosis in mice." (PMID 36551258, 2022). "Accordingly, it was recently shown that L. interrogans serovar Autumnalis strain 56606v, which possesses an LPS atypically devoid of TLR2 activity and signaling only through TLR4, leads to a self-resolving leptospirosis and does not induce kidney colonization in mice." (PMID 32790743, 2020). "Moreover, TLR2 but not TLR4 is responsible for recognizing leptospiral lipopolysaccharide (LPS), the major inducer of inflammatory reactions and immune responses during leptospirosis." (PMID 28700741, 2017). "Aside from TLR2 and TLR4, other TLRs that have not yet been studied in the context of leptospirosis, such as TLR5 that senses flagellin, and TLR9, the receptor of bacterial DNA, could in theory be involved in the murine defense against L. interrogans." (PMID 24498450, 2014). "However, a recent study using humanized TLR4 mice, which are immune competent mice, showed that those mice are not more sensitive to acute leptospirosis, but rather suggested that a functional TLR4 receptor being of mouse or human was required to protect the mice against leptospirosis." (PMID 33705392, 2021). "The data shows that tlr4 competent strains (C3H/HeN and C57BL/6) developed clinical and molecular signs of sublethal leptospirosis not much different than tlr4 hyporesponsive C3H/HeJ." (PMID 40445994, 2025). "The two mouse strains with a functional tlr4 gene (C3H/HeN and C57BL/6) developed clinical and molecular signs of sublethal leptospirosis that were less pronounced but not significantly different than C3H/HeJ." (PMID 40445994, 2025). "Indeed, in contrast with TLR4 knockout (KO) mice, TLR2KO mice do not die from experimental leptospirosis." (PMID 33123147, 2020).
memory impairment (37 papers, 2015 to 2026). "Besides, activation of TLR4 and of the inflammatory pathways leads to glial reaction and neuronal loss, which contributes to memory impairment and behavioral changes." (PMID 31075861, 2019). "Furthermore, mAb 1, mAb 2.5, and mAb 5 suppress second hit PTZ induced seizure and related memory impairment which might be due to an anti-inflammatory associated mechanism of mAb via the modulation of HMGB1/TLR4/NF-κB axis." (PMID 33732146, 2020). "The journal retracts the article "Hesperetin, a Citrus Flavonoid, Attenuates LPS-Induced Neuroinflammation, Apoptosis and Memory Impairments by Modulating TLR4/NF-κB Signaling" [...]." (PMID 41591464, 2026). "The journal retracts the article "Natural Dietary Supplementation of Curcumin Protects Mice Brains against Ethanol-Induced Oxidative Stress-Mediated Neurodegeneration and Memory Impairment via Nrf2/TLR4/RAGE Signaling" [...]." (PMID 41591790, 2026). "Specifically, punicalin has been found to inhibit LPS-induced memory impairment through anti-inflammatory and anti-amyloidogenic mechanisms by inhibiting Toll-Like Receptor-4 (TLR4)-activated NF-κB signalling." (PMID 39683144, 2024). "In studying diseases such as memory impairment and neurological damage after cerebral ischaemia‐reperfusion, animal models of cerebral ischaemic stroke reflect that the TLR4/MyD88/NF‐kB axis is involved in neuroinflammation." (PMID 35393774, 2022). "Juglanin, a flavonol derivative, in LPS-induced C57B/L6 mice potentially modulated IL-1β and TNF-α, and ameliorated neuroinflammation-related memory impairment, and neurodegeneration through impeding TLR4/NF-κB." (PMID 31134076, 2019). "It has been suggested that memory impairment is triggered by direct stimulation of toll-like receptor 4 (TLR4) by LPS." (PMID 25573647, 2015). "Based on these results, we hypothesized that physcion treatment is effective against LPS-induced TLR4 signaling concerning synaptic dysfunction and memory impairment." (PMID 39338361, 2024). "Furthermore, the Aβ oligomers are reported to induce memory impairment in an acute mouse model of AD through Toll-like receptor 4-dependent glial cell activation." (PMID 37410787, 2023). "For instance, Eriodictyol, a natural flavonoid found in citrus fruits and peanuts, has been shown to alleviate neuroinflammation, amyloidogenesis, and memory impairment induced by Lipopolysaccharide (LPS) through many mechanisms, one of which is via inhibiting TLR4 activation." (PMID 35214883, 2022). "MH administration exerted neuroprotective effect against memory impairment and improved locomotor activity in rodents via inhibition of oxidative stress markers/release of proinflammatory cytokines and suppression of protein expression of NF-kB/TLR4/NLRP3." (PMID 36015160, 2022). "Due to its antioxidant and anti-inflammatory properties, hesperetin has shown protective effects against LPS-induced neuroinflammation, neuronal apoptosis, oxidative stress, and memory impairments in C57BL/6 N mice via regulating the toll-like receptor 4 (TLR4)/NF-κB signaling pathways." (PMID 35204122, 2022). "All data confirmed that GB significantly reduced BCCAO induced neuroinflammation and improved neuron survival by reducing the secretion of inflammatory factors via downregulating TLR4/NF-κB pathway, thus alleviating learning and memory impairment in rats with VD." (PMID 34220511, 2021). "Several drugs exert their pharmacological effects through the inhibition of various molecules within the HMGB1/TLR4/NF-κB pathway, resulting in reduced hippocampal inflammatory responses, suppressed microglial activation, mitigated neuronal injury and attenuated surgery-induced memory impairment." (PMID 38975244, 2024). "It has been found that berberine can reduce the levels of NF-κB, TLR4, TNF-α, and IL-6 in the brain of adult male cognitive impairment rats induced by lipopolysaccharide and prevent learning and memory impairment." (PMID 35795239, 2022).